IL6 (interleukin 6)
Diseases named in the same sentence as IL6 in open-access papers (continued):
Sharing a sentence is not in itself a finding about the gene and the disease.
cancer (continued). "KM-LUAD models are vital to understanding the mechanisms of STAT3 and to appraise therapies that block the IL-6/STAT3 signaling pathway across the variety of cancer and immune cells within the TME." (PMID 35406557, 2022). "Myeloid-derived suppressor cells (MDSCs), activated by IL-6, can inhibit T cell responses and promote cancer cell persistence through the JAK/STAT3 signaling pathway." (PMID 36497467, 2022). "IL10 was expressed by malignant tumor cells, inhibiting various immune-related cell populations to achieve immune escape, while the rise of IL6 occurred in inflammation indicated stronger immune response." (PMID 35186744, 2022). "The effect of endogenous and exogenous IL-6 on cancer phenotypes of pre-cancerous human tongue DOK cells and cancerous SCC-4 human tongue cells were also investigated." (PMID 35484352, 2022). "Recently, several IL-6 signaling pathway-targeted monoclonal antibodies have been developed for cancer and immune therapy." (PMID 35924148, 2022). "Since inflammatory cytokines interleukin 1 (IL-1) and interleukin 6 (IL-6) play an important role in the regulation of cancer development, the role of miR-146b in regulating cytokines production in CMTs is worthy of future investigations." (PMID 36359024, 2022). "In a recent study on triple-negative breast cancers (TNBCs), restraining of IL-6 and IL-8 expressions prominently suppressed both in vitro and in vivo cancer cell proliferation." (PMID 35924148, 2022). "IL-6 is an inflammatory cytokine contributing to systemic inflammation and the development of several age-related diseases, e.g., cancer." (PMID 36233472, 2022). "Cancer-associated fibroblasts (CAF) recruit and activate TAMs by secreting proinflammatory cytokines namely, CCL2, CCL3, CCL5, CXCL8, CSF1, CSF2, IL-6, TGF-β, and VEGF." (PMID 36679900, 2022). "High levels of IL-6 have been associated with a poor prognosis in various human cancers, and within the TME, IL-6 promoted cancer cell proliferation, angiogenesis, and immunosuppression." (PMID 35878391, 2022). "In this context, the pro-inflammatory cytokines, tumor necrosis factor-α (TNF-α) and interleukin (IL)-6 (a major inducer of CRP), as well as the immunosuppressive cytokine, IL-10, have all been implicated in both the initiation and development of cancer." (PMID 35223501, 2022). "Blockade of the IL-6/IL-6R signaling pathway has become a promising target for the therapy of cancers and inflammatory autoimmune diseases." (PMID 36419076, 2022). "Our research explored the possible association between IL-6 and IDO1 in the progress of HPV-related tumors, as well as their influence on a specific cancer immunotherapy strategy." (PMID 36405719, 2022). "In the model, TC is considered the primary inhibitor of the cancer cells, and IL6 and A are the main contributors to their production." (PMID 35629230, 2022). "Several studies have revealed correlations between fatigue and cytokine levels, mainly IL-6, in cancer patients and have been positively correlated with cognitive and somatic fatigue, particularly in cancer patients." (PMID 36139563, 2022). "All plasma levels of neutrophil number, neutrophilic percentage, IL-1β, IL-8, and IL-6 in cancer patients with metastases were significantly higher than those without metastases (P < 0.05 for all)." (PMID 36157224, 2022). "TNF-α and IL-6 are multifunctional cytokines involved in chronic inflammation and contribution to the progression of cancer." (PMID 35444660, 2022). "As was demonstrated in vitro, the production of IL-6 by CAFs is precisely controlled in the co-culture of cell lines from the ductal cancer of the pancreas and CAFs isolated from the same cancer type." (PMID 35055153, 2022). "In the model, either cancer cells production happens independently or is promoted by adipocytes and IL6." (PMID 35294447, 2022). "Dysregulation of IL-6 and key downstream signaling pathways are common events in cancer and portend an adverse outcome." (PMID 36182930, 2022).
cancer (continued). "This causes the secretion of TGFβ and IL-6 among other factors, which will again result in the promotion of EMT and stemness in cancer cells." (PMID 35159370, 2022). "By increasing ROS generation, MMA induces a secretory signature in CAFs wherein IL-6 delivered in EVs drives metastatic signaling and progression of epithelial-like (or primary) cancer cells." (PMID 36266345, 2022). "IL-6 is secreted mainly by monocytes, and also by macrophages, Kupffer cells, keratinocytes, endothelial cells, B and T cells, and cancer cells." (PMID 36289922, 2022). "CD10+GPR77+ CAFs constantly secrete IL-6 and IL-8 through activating the NF-KB signaling pathway, providing a survival niche for cancer stem cells." (PMID 36627901, 2022). "As a classical inflammatory factor, IL-6 is also involved in the regulation of inflammation and cancer." (PMID 35664068, 2022). "MDSC levels in patients with active TB were comparable to those in patients with cancer and contributed to reduced Th1 cytokine expression, whereas proinflammatory cytokines, such as IL-1β, IL-6, IL-8, and monocyte chemoattractant protein-1, were increased." (PMID 35092727, 2022). "We uncovered an unpredicted immunosuppressive function of IL-6/STAT3 pathway in cancer cells affecting the expression of potent neoantigens under the control of NMD." (PMID 36443756, 2022). "Anamorelin (appetite stimulation), megestrol acetate, eicosapentaenoic acid, phytocannabinoids, targeting MSTN/activin, and molecules targeting proinflammatory cytokines, such as TNF-α and IL-6, are being tested as treatment options for cancer cachexia." (PMID 35565236, 2022). "IL-6 represents the degree of inflammation in cancer tissue, and IL-6 elevation leads to increased CRP and decreased serum albumin." (PMID 36260237, 2022). "CAFs have also been demonstrated to induce EMT and promote the growth and migration of cancer cells via IL-6." (PMID 36010899, 2022). "In advanced stages of cancer, IL-6 induces transcriptional activators of EMT (zinc finger proteins Snail1 and Twist), accelerating the metastatic spread of invasive cancer cells." (PMID 36313280, 2022). "Tumors with low stromal IL-6 and high cancer cell LC3 expression have a better response to chemotherapy than tumors with any other combination." (PMID 36362726, 2022). "Among these cytokines, the concentration of IL-6 was the highest in the peripheral blood of cancer patients, showing an increase of approximately sevenfold." (PMID 36072935, 2022). "IL-6 is a mediator of systemic inflammatory responses not only in cancer and HF but also in other inflammatory and infectious diseases." (PMID 35967380, 2022). "Increased levels of pro-cachectic cytokines, such as interleukin (IL)-1, IL-1α, IL-6 and tumor necrosis factor-α (TNF-α) are associated with weight loss, skeletal muscle catabolism and apoptosis in cancer cachexia." (PMID 35204066, 2022). "PMN-MDSCs and M-MDSCs are activated by prolonged stimulation that is mediated by growth factors and pro-inflammatory cytokines (GM-CSF, CSF1, IL-6, and 1L-1β), as seen in conditions such as cancer, chronic infections, and autoimmune diseases." (PMID 36532078, 2022). "Particularly, cancer-associated fibroblasts (CAFs) that predominantly accumulate in the stroma of the tumor microenvironment (TME) of gastric (GC), pancreatic (PC), and hepatic cancers stimulate the EMT of cancer cells via interleukin-6 and TGF-β1 secretion." (PMID 36428576, 2022). "Interleukin-6 (IL-6), an important inflammatory cytokine, is a key factor regulating cancer metastasis." (PMID 35432524, 2022). "As a transcription factor, AP-1 is also involved in the production of inflammatory cytokines such as IL-6 and TNFα, which supports the malignant phenotype of cancer cells." (PMID 35964097, 2022). "In a review paper, the IL-6 serum level at diagnosis was significantly correlated to survival in 82/101 series comprising 9917 out of 11,583 patients with 23 different cancer types, including HNSCC patients." (PMID 36289746, 2022).
cancer (continued). "The dual inhibition sustained an increased production of IFNγ, TNFα, IL-12 and IL-6 by PBMCs, that contribute to expression of Ido-1 on cancer cells." (PMID 36419183, 2022). "Chronic systemic inflammation mediated by cancer-induced cytokines (IL-6, IL-10) is reflected in the increase in the number of circulating platelets." (PMID 35268305, 2022). "Several studies have also investigated the function of IL-6 in promoting resistance to chemotherapeutic agents in a variety of cancers, including GC." (PMID 35884907, 2022). "In cancer, IL-6 trans-signaling induces therapeutic resistance, angiogenesis, and is associated with poor clinical outcome." (PMID 35371975, 2022). "In HCC and other cancer types, several studies have shown the critical involvement of inflammation, especially of interleukin-6 (IL-6) signaling during carcinogenesis." (PMID 35267462, 2022). "As established major soluble mediator of inflammation, IL-6 is crucial in governing cancer-related inflammation, including in PCa." (PMID 36338516, 2022). "Serum levels of inflammatory markers like CRP, IL-6 and TNF are associated with the incidence of several cancers and mortality in cohorts and meta-analyses in the general population, with a modest effect size." (PMID 35406394, 2022). "IL-6 is known to be involved in various liver pathologies, especially liver regeneration and cancer." (PMID 35205631, 2022). "In detail, RV keeps the cancer cells in an autophagy-mediated dormant-like state contrasting the IL-6 pro-growth activity." (PMID 35565270, 2022). "The cytokine IL-6, as expressed through nuclear factor (NF)-κB/Stat3 signaling, facilitates cancer initiation by enhancing the proliferation of tumor-initiating cells." (PMID 35681791, 2022). "Blocking IL-6 signaling leads to decreased wasting of muscles and prevents cancer cachexia in melanoma and prostate tumor cachectic mouse models." (PMID 35967380, 2022). "CAFs promotes EMT and resistance to cisplatin in non-small cell lung cancer (NSCLC) via the TGF-β/IL-6 axis; cisplatin treatment also increases the secretion of TGF-β in cancer cells, leading to CAFs activation and increased IL-6 secretion." (PMID 36313280, 2022). "In summary, IL-6 signaling plays a regulatory role in controlling cancer cell growth, CSC renewal and metastasis." (PMID 35924148, 2022). "Baseline creatinine, and inflammatory markers, D-dimers, ferritin and IL-6 of patients with cancer who underwent chemotherapy before SARS-CoV-2 infection." (PMID 35360723, 2022). "In cancer, TAMs were reported to secrete IL-6 via STAT3 pathway leading to expansion of cancer stem cells and breast cancer progression." (PMID 36325334, 2022). "Proinflammatory factors such as IL-1, IL-6, IL-8, and TNFα generally enhance the occurrence and development of cancer by activating growth, metastasis, and invasion." (PMID 35443863, 2022). "Succinate-induced macrophage polarization augments cancer cell migration by secreting pro-migratory cytokines such as interleukin-6 (IL-6)." (PMID 36344992, 2022). "Under inflammatory conditions, NF-κB-induced IL-6 can lead to cancer progression and metastasis via the IL-6/STAT3 signaling pathway." (PMID 35749000, 2022). "Berberine-induced inhibition of the TLR4/NF-κB/IL-6/STAT3 pathway reduced malignant transformation and cancer recurrence in colitis-associated colorectal carcinoma models." (PMID 36700235, 2022). "Interleukin 6 (IL-6) is a pleiotropic cytokine that is involved in the regulation of the growth of the majority of malignant tumours, including PCa." (PMID 35326402, 2022). "In breast cancer, higher expression of miR-25-3p in hypoxic cancer-derived exosomes was found to stimulate cancer proliferation and migration by inducing IL-6 secretion and activating NF-κB signaling in macrophages." (PMID 36176760, 2022). "Pro-inflammatory cytokines such as IL-6 and TNFα that are released by TAMs, finally enhance cell migration and tissue invasion favoring cancer cell dissemination." (PMID 35847862, 2022).
cancer (continued). "We found that SHC1 was associated with abundant signaling pathways in pan-cancer, such as TNFA-NFKB, inflammatory response, IL6-JAK-STAT3, hypoxia, EMT, apical junction, and angiogenesis." (PMID 35935986, 2022). "Cancer cells themselves secrete cytokines related to inflammation, such as IL-1α, IL-6, and IL-8, which can activate macrophages." (PMID 35855902, 2022). "IL-6 is overexpressed in a variety of cancer cells, and cancer cells rely extensively on IL-6 signal transduction." (PMID 35222443, 2022). "When cachectic (weight‐losing) individuals were compared with non‐cachectic (weight‐stable) cancer patients, five out of eight studies indicated that the levels of IL‐6 were significantly higher in cachectic participants." (PMID 35080147, 2022). "In another study, the infiltrated inflammatory monocytes induced blood vessel formation, cancer cell proliferation in metastasis, and IL-6 production in mice." (PMID 35267547, 2022). "ApcMin/+ mice display increased gut barrier permeability, whom onset correlates with IL-6 blood levels and cancer cachexia manifestation." (PMID 36158184, 2022). "The four PRGs—CASP5, CASP8, IL6, and TIRAP—in this PPS were found to be closely associated with the development of cancers." (PMID 35255915, 2022). "By producing cytokines, including TNF-α, IL-12, and IL-6, M1 macrophages have an anti-cancer effect, but M2 macrophages promote the proliferation of cancer cells by producing IL-10, TGF-α." (PMID 36298592, 2022). "Several possible explanations exist, such as the implication of TGF-β and IL-6 and the development of chronic inflammation that results in cancer immune evasion through T cell exhaustion." (PMID 35774996, 2022). "Among numerous cancer-derived factors, IL6, TGFβ, and PDGF are the widely accepted fibroblast-activating factors that promote the activity of downstream signaling pathway, such as the SMAD and NF-κB signaling." (PMID 35155261, 2022). "In OSCC cells, P. gingivalis stimulates the release of a variety of chemokines and cytokines contributing to cancer, namely, IL-1β, IL-6, IL-8, TGF-β1, EGF, and TNF-α." (PMID 35847109, 2022). "Consistently, the levels of angiogenic factors, such as VEGF, IL-6, TSP-1, PF4, TGFβ, and PDGFβ were linked not only with the platelet count but also with cancer stage and patient prognosis." (PMID 36362186, 2022). "Activation of IL-6/JAK2/STAT3 pathway is closely associated with EMT and stem cell-like features, ultimately leading to poor outcomes in various human cancer patients." (PMID 36591515, 2022). "The invasion of fat by cancer cells is known to secrete various adipokines such as leptin, adiponectin, IL-6, CCL2, and CCL5." (PMID 35123536, 2022). "More recently, because the IL-6-STAT3 signaling pathway can be directly involved in progression and metastasis of prostate cancer, evaluation of IL-6 and its receptor as targets for cancer treatment is currently being explored." (PMID 36275816, 2022). "In breast cancer, CAF-produced IL-6 acts in a paracrine manner on cancer cells, inducing expansion of the stem cell pool via JAK1/STAT3 signaling and evasion from targeted therapy." (PMID 36324182, 2022). "The JAK/STAT pathway plays a critical role in solid tumour progression and thus inhibition of downstream events by IL-6 or IL-6R blockage is a promising strategy for the development of new anti-cancer combination therapies." (PMID 36439165, 2022). "Anti-IL-6 antibody-mediated blockage of IL-6 signaling partially reversed the efficacy of exercise on inhibition of cancer cell proliferation." (PMID 35246220, 2022). "Osteoclasts are formed and activated by cytokines derived from cancer cells, such as PTHrP, interleukin (IL)-1, IL-6, and IL-8, which activate the RANK/RANKL (receptor activator of NF-κB ligand) signaling mechanism." (PMID 35149903, 2022).
cancer (continued). "Similar to IL-6, IL-8 and CXCR2 signaling was shown to affect cancer-associated fibroblasts and cause increased secretion of pro-tumorigenic cytokines mediated by the nuclear factor kappa-light-chain-enhancer of activated B cells (NF-κB) transcription factor." (PMID 35965494, 2022). "In fact, potential IL-6 inhibitors have been evaluated extensively for therapeutic efficacy against various cancers." (PMID 35720420, 2022). "Early studies found that expression of members of the interleukin (IL) family of cytokines, such as IL-6 and IL-8, was strongly correlated with cancer relapse and a poor response to chemotherapy." (PMID 35289315, 2022). "Briefly, BAs on the one hand stimulate/reduce the secretion of inflammatory factors such as IL-6 and TNF-α, thereby activating/inactivating signaling pathways associated with cancer promotion to improve/inhibit cancer growth or invasiveness." (PMID 36338764, 2022). "Many inflammatory factors like IL-1β, TGF-β, IL-6 can regulate the DNA methylation patterns that induce cancer initiation and progression in cancers such as gastric cancer, ovarian cancer, and liver cancer." (PMID 36225315, 2022). "The TCLs from these apoptotic cancer cells effectively activated monocyte-derived DCs, showing significantly facilitated gene expression levels of IL-12 and IL-6 cytokines compared to TCLs from lipopolysaccharide (LPS)-treated cancer cells." (PMID 35890254, 2022). "This is due to the fact that macrophages produce IL6 and IL10, which, respectively, cause cancer cell proliferation and inhibition of cytotoxic T cells." (PMID 35629230, 2022). "TNF-α in cancer-related fibroblasts and hepatic fibroblasts strongly triggers the IL-6 and MCP-1 expression levels, which in turn create a prometastatic microenvironment." (PMID 35954156, 2022). "Regulatory and suppressive immune cells can be recruited to the virus-infected sites and cancer microenvironments through various factors, including cytokines IL-6 and IL-10, as well as growth factors like VEGF and PGE2." (PMID 36010256, 2022). "Compared with factors of IL6, TNFα seems to be less determinate in predicting the outcomes of cancer survival." (PMID 35859928, 2022). "IL-6 overexpression has been reported in many cancers, including HCC, where it is suggested to promote the transition of fibroblasts to CAFs68." (PMID 35568708, 2022). "It is therefore likely that localized cancer arising within the native prostate tissue benefits from sustained local inflammatory networks driven by IL-6, TNFα and SELE." (PMID 36371231, 2022). "Quiescent endothelial cell secretions, mediated through perlecan, inhibit the proliferation and IL-6-mediated invasion of lung and BC cells, and cancer cell pro-tumorigenic and pro-inflammatory signaling in vitro." (PMID 35884405, 2022). "High plasma IL-6 affects both cancer specific outcomes (relapse and survival) and patient-centered outcomes as functional decline (performance status, decreased mobility, deficits in instrumental activities of daily living)." (PMID 36233472, 2022). "Baseline creatinine, and inflammatory markers, D-dimers, ferritin and IL-6 of non-cancer SARS-CoV-2 infected patients after discharged from hospital." (PMID 35360723, 2022). "TGF-β can induce MSCs to produce inflammatory Interleukin-6 (IL-6), and IL-6 is known to increase cancer-promoting functions in MSCs." (PMID 34996476, 2022). "It highlights the possibility of using IL-6/STAT3/SMG1 pharmacological inhibitors to sensitize them for cancer immunotherapy." (PMID 36443756, 2022). "The IL-6/STAT3 signaling pathway consistently demonstrates aberrant hyper-activation in cancer patients." (PMID 34976184, 2022). "It was found that the risk factors of the increased prevalence of CRCI were normally involved in social–demographic factors, cancer-therapy-related factors, psychological factors, and some cytokines including IL-6, TNF-α, sTNRFII, etc.." (PMID 35448193, 2022).